TMOD3 (tropomodulin 3)
Description:
Blocks the elongation and depolymerization of the actin filaments at the pointed end. The Tmod/TM complex contributes to the formation of the short actin protofilament, which in turn defines the geometry of the membrane skeleton (By similarity).
Synonyms: UTMOD
Tractability: PROTAC: ubiquitination databases record sites on it; its protein half-life has been measured.
Gene: Protein-coding gene on chromosome 15 (51,829,628 to 51,947,295, forward strand). Ensembl gene ENSG00000138594.
Subcellular location: Cytoplasm, cytoskeleton
Subcellular location (Human Protein Atlas): Cytosol; Actin filaments
Pathways (Reactome):
Signal Transduction: RHOBTB2 GTPase cycle; RND3 GTPase cycle
Muscle contraction: Striated Muscle Contraction
Gene Ontology:
Molecular function: cadherin binding involved in cell-cell adhesion; protein binding; actin binding; tropomyosin binding
Biological process: actin filament organization; muscle contraction; myofibril assembly; cell-cell adhesion; pointed-end actin filament capping
Cellular component: adherens junction; cytoskeleton; striated muscle thin filament
Genetic constraint (gnomAD): Loss-of-function variants: 16 observed, 31.63 expected, observed/expected ratio (o/e) 0.51, 90% interval 0.34 to 0.77. The upper end of that interval is the gene's LOEUF score, 0.77, which puts it in group 3 of 6, group 1 being the genes least tolerant of losing a copy. Missense variants: 331 observed, 374.27 expected, observed/expected ratio (o/e) 0.88, 90% interval 0.81 to 0.97. Synonymous variants: 134 observed, 136.64 expected, observed/expected ratio (o/e) 0.98, 90% interval 0.85 to 1.13.
Homologues: Orthologues: chimpanzee TMOD3 (99% identical), macaque TMOD3 (98% identical), dog TMOD3 (95% identical), pig TMOD3 (92% identical), mouse Tmod3 (90% identical), guinea pig TMOD3 (90% identical), rat Tmod3 (88% identical), zebrafish tmod2 (71% identical), tropical clawed frog tmod3 (70% identical), Caenorhabditis elegans unc-94 (36% identical), Drosophila melanogaster tmod (24% identical). Paralogues in human: TMOD2 (76% identical), TMOD1 (61% identical), TMOD4 (54% identical), LMOD2 (40% identical), LMOD1 (37% identical), LMOD3 (34% identical).
Diseases named in the same sentence as TMOD3 in open-access papers:
TMOD3 is named in the same sentence as 27 diseases in open-access papers, as found by Europe PMC text mining. Sharing a sentence is not in itself a finding about the gene and the disease. The quoted sentences say what the papers report.
endometriosis (4 papers, 2015 to 2025). The growth of functional endometrial tissue in anatomic sites outside the uterine body. "Serological tests using anti-TPM3 and anti-TMOD3 antibodies demonstrated higher sensitivity, specificity, and accuracy in diagnosing early stages of endometriosis (stages I and II) compared to the commonly used marker CA125." (PMID 40072086, 2025). "Autoantibodies against different epitopes of tropomyosin 3 (TPM3), stomatin-like protein 2 (SLP2), and tropomodulin 3 (TMOD3) were significantly elevated in the serum of endometriosis patients with both minimal/mild and moderate/severe disease." (PMID 26240814, 2015). "Elevated levels of IgM to TPM3 and IgG to TMOD3 were observed in patients with ovarian cysts, while only IgM to TPM3 was elevated in deep infiltrative endometriosis patients." (PMID 40072086, 2025).
glioma (3 papers, 2022 to 2024). A benign or malignant brain and spinal cord tumor that arises from glial cells (astrocytes, oligodendrocytes, ependymal cells). "Tmod3 cleavage by legumain produces functional truncated Tmod3 which is detected in various tumors and associated with poor prognosis of high-grade glioma." (PMID 36555634, 2022). "Truncated Tmod3 was detected in diverse tumors and was found to be associated with poor prognosis of high-grade glioma." (PMID 35765111, 2022). "The specific cleavage of Tmod3 can be detected in array of solid tumors, and the cleavage of Tmod3 is significantly associated with poor prognosis in high grade glioma (HGG)." (PMID 35765111, 2022). "We further detected the expression of Tmod3 by immunohistochemical staining in a tissue array of 123 human glioma specimens." (PMID 35765111, 2022). "We collected 72 human freshly frozen glioma tissues (LGG, 24; HGG, 48), 8 normal brain tissues, 25 hepatocellular carcinoma and 30 cervical cancer tissues to detect the cleavage of Tmod3 by western blotting." (PMID 35765111, 2022). "Western blotting analysis of glioma tissues consistently showed that Tmod3 was significantly upregulated in HGG compared to LGG and normal brain tissues." (PMID 35765111, 2022).
pancreatic cancer (3 papers, 2023 to 2026). "It has been shown that tropomodulin-3 (TMOD3) may influence tumor progression, but its role in pancreatic cancer is not clear." (PMID 37563820, 2024).
breast carcinoma (2 papers, 2021 to 2025).
glioblastoma (2 papers, 2025). The most malignant astrocytic tumor (WHO grade IV).
hepatocellular carcinoma (2 papers, 2021 to 2022). A malignant tumor that arises from hepatocytes. "The cleavage of Tmod3 was also detected in the hepatocellular carcinoma tissues (32.0%, 8 of 25 cases) and the cervical cancer tissues (26.7%, 8 of 30 cases)." (PMID 35765111, 2022). "TMOD3 is a tumor suppressor target and an independent prognostic marker of PDAC, and its overexpression in hepatocellular carcinoma correlates with tumor progression and poor patient survival, and TMOD3-knockout liver cancer cells have decreased proliferation, invasion and migration." (PMID 33648511, 2021).
liver cancer (2 papers, 2021 to 2022). An epithelial or non-epithelial malignant neoplasm that arises from the liver. "In addition, TMOD3 thought to promote liver cancer progression via MAPK/ERK signaling." (PMID 35957868, 2022).
lung carcinoma (2 papers, 2024 to 2025). "Additionally, we found that Tmod3 was highly expressed in lung cancer cells and that knocking out Tmod3 enhanced the sensitivity of A549/PTX cells to paclitaxel, paralleling CDC6 depletion phenotypes." (PMID 41339304, 2025).
pancreatic adenocarcinoma (2 papers, 2022 to 2024). "Tmod3 was found to be upregulated in diverse types of tumors such as cholangio carcinoma (CHOL), pancreatic adenocarcinoma (PAAD) and stomach adenocarcinoma (STAD), compared to the corresponding normal tissues." (PMID 35765111, 2022).
Alzheimer disease (1 paper, 2025). A progressive, neurodegenerative disease characterized by loss of function and death of nerve cells in several areas of the brain leading to loss of cognitive function such as memory and language. "Single-cell validation confirmed vascular-endothelial dysfunction, with LAMC1, RBMS2 and TMOD3 upregulated in endothelial cells from female APOE ε4 Alzheimer’s disease brains." (PMID 41409615, 2025).
anemia (1 paper, 2016). A reduction in the number of red blood cells, the amount of hemoglobin, and/or the volume of packed red blood cells. "In the case of Tmod3 knockout mouse, deletion of Tmod3 caused the embryonic lethality at E14.5-E18.5, presumably by anemia caused by impairment of erythroid development." (PMID 27374327, 2016).
Arterial thrombosis (1 paper, 2023). The formation of a blood clot inside an artery. "Moreover, a previous study demonstrated that BCAAs significantly enhanced platelet activity in human and promoted arterial thrombosis formation in mice, and the increased tropomodulin-3 propionylation mediated by BCAAs metabolic products played an essential role in this process." (PMID 37805555, 2023).
cervical squamous cell carcinoma (1 paper, 2022). A squamous cell carcinoma arising from the cervical epithelium. "High Tmod3 expression is associated with poor patient prognosis in many types of tumors, including GBM and LGG, cervical squamous cell carcinoma and endocervical adenocarcinoma (CESC), lung adenocarcinoma and adenosquamous carcinama (LUAD and LUSC), PAAD and bladder urothelial carcinoma (BLCA)." (PMID 35765111, 2022).
Chlamydia infection (1 paper, 2019). "The remaining 6 proteins identified by all 3 MS approaches–ASPH, LRRF1, LRC59, TMOD3, CLINT1, and BAP31–represent priority targets for further study in the context of Chlamydia infection." (PMID 30943267, 2019).
endothelial dysfunction (1 paper, 2025). In vascular diseases, endothelial dysfunction is a systemic pathological state of the endothelium (the inner lining of blood vessels) and can be broadly defined as an imbalance between vasodilating and vasoconstricting substances produced by (or acting on) the endothelium. "LAMC1, RBMS2, TMOD3, and LRP10 were suggested as key drivers of AD progression associated with endothelial dysfunction." (PMID 41409615, 2025).
melanoma (1 paper, 2020). A malignant, usually aggressive tumor composed of atypical, neoplastic melanocytes. "The TMOD3/RAI14/VWF axis interacts with the cytoskeleton in prostate cancer, and Liu and colleagues revealed that cell migration and the invasion of melanoma was impaired by RAI14 depletion via regulating the AFAP1-AS1/miR-653-5p/RAI14 axis." (PMID 32957082, 2020).
tumor (11 papers, 2016 to 2025). "Tmod3 KD reduced weight loss and prolonged the OS of tumor-bearing mice." (PMID 35765111, 2022). "Furthermore, higher expression levels of ADAM9, EFNB2, MET, and TMOD3 were significantly associated with increased tumor infiltration of macrophages, DCs and/or B cells." (PMID 33648511, 2021). "Since truncations of Tmod3 are present in tumor tissues and are prognostically relevant, what is their function?" (PMID 35765111, 2022). "The present study suggests that the cell proliferation regulation by AEP through Tmod3 truncation also provides a practical basis for therapies targeting tumor proliferation." (PMID 35765111, 2022). "Studies have reported that Tmod3 is a potential tumor suppressor protein, which is compatible with its structure and functions." (PMID 35765111, 2022). "Our work directly elucidates that the tumor-promoting effects of Tmod3 are mediated by the truncations induced by AEP." (PMID 35765111, 2022). "Single cell/nuclear-sequences were done to detect the heterogeneous expression of Tmod3 in tumor tissues." (PMID 35765111, 2022). "Six overexpressed and mutated tumor antigens associated with poor prognosis and infiltration of antigen presenting cells were identified in PAAD, including ADAM9, EFNB2, MET, TMOD3, TPX2, and WNT7A." (PMID 33648511, 2021). "Therefore, the detection of specific cleavage of Tmod3 in clinical samples can be used as an important biomarker for evaluating tumor malignancy." (PMID 35765111, 2022). "Animal models further revealed the tumor-promoting effects of AEP truncated Tmod3 in vivo." (PMID 35765111, 2022). "Together, these results suggested that two truncations of Tmod3 may promote GBM cancer cell malignancy in different ways: tTmod3-C mainly promotes tumor proliferation, while tTmod3-N primarily promotes invasion." (PMID 35765111, 2022). "We have established a four molecular pathway foundation (ANXA2/HMGA1/POU3F1; NFRSF13/GSN; TMOD3/RAI14/VWF; PLAT/PLAU) behind HO-1 regulation of the tumor cytoskeletal compartments." (PMID 32640729, 2020). "The integration from our omics-based research provides a four molecular pathway foundation (ANXA2/HMGA1/POU3F1; NFRSF13/GSN; TMOD3/RAI14/VWF; and PLAT/PLAU) behind HO-1 regulation of tumor cytoskeletal cell compartments." (PMID 28032857, 2016). "We found that age, sex, cancer recurrence, WHO tumor grade and isocitrate dehydrogenase 1 (IDH1) mutation were without difference in patients with or without Tmod3 cleavage." (PMID 35765111, 2022). "Genes CBX3, RCC1, TMOD3, and NOA1 (Cluster A) and TOP1, PDCD5, and THRAP3 (Cluster B) were upregulated for both datasets in PCa tissue vs. normal gland or normal adjacent to tumor tissue." (PMID 32640729, 2020). "Strikingly, when integrating the transcriptome under HO-1 modulation with the HO-1 interactome, a framework of four main molecular pathways arose as the foundation for the regulation of the tumor cell protrusive forces: ANXA2/HMGA1/POU3F1; NFRSF13/GSN; TMOD3/RAI14/VWF; PLAT/PLAU." (PMID 28032857, 2016).
cancer (6 papers, 2021 to 2025). A tumor composed of atypical neoplastic, often pleomorphic cells that invade other tissues. "These two truncations played completely different roles in promoting cancer than those exhibited by Tmod3 through actin remodeling and SND1/RhoA-mediated cell proliferation." (PMID 35765111, 2022). "Results of cellular functional assays consistently showed that truncated Tmod3 mediates the AEP-enhanced aggressive phenotype of cancer cells." (PMID 35765111, 2022). "Taken together, these results indicate that AEP interacts with Tmod3 and cleaves at N157, generating two Tmod3 truncations with complete functional domains in cancer cells." (PMID 35765111, 2022). "Truncations of Tmod3 induced by AEP contribute to cancer progression by facilitating actin remodeling and nuclear SND1 mediated RhoA/CDKs transcription." (PMID 35765111, 2022). "To identify the functions of Tmod3 in cancer cells, we constructed Tmod3-knockdown (KD) U87-MG and A172 cells using lentivirus." (PMID 35765111, 2022). "Our work provides new clues to the underlying mechanisms of cancer proliferation and invasive progression and evidence for targeting AEP or Tmod3 for therapy." (PMID 35765111, 2022). "In biochemical experiments, Tmod3 was found to be cleaved by AEP in cancer cells." (PMID 35765111, 2022). "In the present study, we demonstrate that AEP specifically cleaves Tmod3 at N157 and produces two truncated Tmod3 proteins, which regulate the invasion and proliferation of cancer cells through cytoplasmic actin remodeling and nuclear SND1/RhoA signaling, respectively." (PMID 35765111, 2022). "However, few studies have explained the mechanisms by which Tmod3 plays a cancer-promoting effect in tumors." (PMID 35765111, 2022). "Taken together, the results suggested that Tmod3 may exert deleterious effects in different types of solid tumors, and that suppression of Tmod3 significantly inhibits the malignancy-related functions of GBM cancer cells in vitro and in vivo." (PMID 35765111, 2022). "Hence, these findings demonstrated that tTmod3-N remodeled the actin cytoskeleton by interacting with actin and competitively suppressing full-length Tmod3 functions, which significantly promoted the invasion of cancer cells." (PMID 35765111, 2022). "In addition, starting with the goal of understanding unique properties of GBM, we delineate a pan-cancer rule based on specific enzymatic activation of Tmod3 by AEP." (PMID 35765111, 2022).
TMOD3 also shares sentences with these, for which no sentence is quoted: bacterial infection (1 paper); cervical cancer (1); endocervical adenocarcinoma (1); infection (1); lung adenocarcinoma (1); pancreatic ductal adenocarcinoma (1); prostate carcinoma (1); pulmonary hypertension (1); stomach adenocarcinoma (1).